METTL14 (methyltransferase 14, N6-adenosine-methyltransferase non-catalytic subunit)
Description:
The METTL3-METTL14 heterodimer forms a N6-methyltransferase complex that methylates adenosine residues at the N(6) position of some mRNAs and regulates the circadian clock, differentiation of embryonic stem cells and cortical neurogenesis. In the heterodimer formed with METTL3, METTL14 constitutes the RNA-binding scaffold that recognizes the substrate rather than the catalytic core. N6-methyladenosine (m6A), which takes place at the 5'-[AG]GAC-3' consensus sites of some mRNAs, plays a role in mRNA stability and processing. M6A acts as a key regulator of mRNA stability by promoting mRNA destabilization and degradation (By similarity). In embryonic stem cells (ESCs), m6A methylation of mRNAs encoding key naive pluripotency-promoting transcripts results in transcript destabilization (By similarity). M6A regulates spermatogonial differentiation and meiosis and is essential for male fertility and spermatogenesis (By similarity). M6A also regulates cortical neurogenesis: m6A methylation of transcripts related to transcription factors, neural stem cells, the cell cycle and neuronal differentiation during brain development promotes their destabilization and decay, promoting differentiation of radial glial cells (By similarity).
Synonyms: hMETTL14; KIAA1627
Tractability: Small molecule: a structure with a bound ligand is known; a high-quality ligand is known. PROTAC: ubiquitination databases record sites on it; its protein half-life has been measured; a small molecule that binds it is known.
Gene: Protein-coding gene on chromosome 4 (118,685,387 to 118,715,433, forward strand). Ensembl gene ENSG00000145388.
Subcellular location: Nucleus
Subcellular location (Human Protein Atlas): Nucleoplasm
Pathways (Reactome):
Metabolism of RNA: Processing of Capped Intron-Containing Pre-mRNA
Gene Ontology:
Molecular function: mRNA binding; mRNA m(6)A methyltransferase activity; protein binding; S-adenosyl-L-methionine binding; catalytic activity, acting on a nucleic acid; S-adenosylmethionine-dependent methyltransferase activity
Biological process: mRNA modification; mRNA processing; mRNA splicing, via spliceosome; mRNA stabilization; negative regulation of hematopoietic progenitor cell differentiation; positive regulation of translation; DNA damage response; forebrain radial glial cell differentiation; gliogenesis; mRNA destabilization; primary miRNA processing; regulation of T cell differentiation; RNA methylation; spermatogenesis; stem cell population maintenance; regulation of neuron differentiation; regulation of RNA stability; response to nutrient levels
Cellular component: nucleoplasm; nucleus; RNA N6-methyladenosine methyltransferase complex
Genetic constraint (gnomAD): Loss-of-function variants: 16 observed, 31.94 expected, observed/expected ratio (o/e) 0.5, 90% interval 0.34 to 0.76. The upper end of that interval is the gene's LOEUF score, 0.76, which puts it in group 3 of 6, group 1 being the genes least tolerant of losing a copy. Missense variants: 208 observed, 366.34 expected, observed/expected ratio (o/e) 0.57, 90% interval 0.51 to 0.64. Synonymous variants: 107 observed, 123.95 expected, observed/expected ratio (o/e) 0.86, 90% interval 0.74 to 1.01.
Homologues: Orthologues: chimpanzee METTL14 (100% identical), dog METTL14 (99% identical), macaque METTL14 (99% identical), pig METTL14 (99% identical), guinea pig METTL14 (99% identical), mouse Mettl14 (99% identical), rat Mettl14 (98% identical), rabbit METTL14 (95% identical), zebrafish mettl14 (83% identical), tropical clawed frog mettl14 (81% identical), Drosophila melanogaster Mettl14 (57% identical).
Diseases named in the same sentence as METTL14 in open-access papers:
METTL14 is named in the same sentence as 236 diseases in open-access papers, as found by Europe PMC text mining. Sharing a sentence is not in itself a finding about the gene and the disease. The quoted sentences say what the papers report.
hepatocellular carcinoma (128 papers, 2017 to 2026). A malignant tumor that arises from hepatocytes. "Both breast cancer (BC) and hepatocellular carcinoma (HCC) that express the human epidermal growth factor receptor 2 (HER2) are associated with METTL14." (PMID 40271153, 2025). "In hepatocellular carcinoma, METTL14 directly binds to and installs m6A on circSTX6, and the regulatory effect disappears when m6A sites are mutated, indicating METTL14-dependent m6A regulation of circRNA." (PMID 41323393, 2025). "As a central component of the N6-methytransferase complex, METTL14 has been implicated in a variety of cancers, including gastric cancer 29, colorectal cancer 30, 31, hepatocellular cancer 32 and other types of cancers." (PMID 37215454, 2023). "A recent study shows that METTL14 is decreased in hepatocellular carcinoma (HCC) and is associated with metastasis in vivo and in vitro." (PMID 35886072, 2022). "For example, METTL14 deficiency reduced m6A modification level in hepatocellular carcinoma (HCC) and participated in the metastasis process of HCC." (PMID 33314339, 2021). "Specifically, downregulation of METTL14 in hepatocellular carcinoma (HCC) is associated with reduced miR-126a levels and increased metastatic capacity." (PMID 32411802, 2020). "In a recent study, the downexpression of METTL14 has been reported to act as an adverse prognosis factor for recurrence‐free survival of hepatocellular carcinoma and be associated with tumor metastasis in vitro and in vivo." (PMID 31429529, 2019). "Although METTL14 promotes metastasis by increasing m6A on PERP mRNA in pancreatic cancer metastasis, it often acts as a metastasis suppressor in colorectal and hepatocellular carcinoma, where loss of METTL14 leads to EMT and stemness through reduced m6A abundance on key transcripts." (PMID 41301491, 2025). "Indeed, in glioblastoma and hepatocellular carcinoma, METTL14 downregulation associated with m6A levels reduction, while VIRMA upregulation positively correlated with higher m6A levels, in both testicular germ cell tumors and prostate cancer." (PMID 35048498, 2022). "In contrast, METTL14 overexpression is associated with suppressed metastasis in hepatocellular carcinoma (HCC)." (PMID 41157107, 2025). "Also, downregulated METTL14 was associated with malignant phenotypes of hepatocellular cancer." (PMID 36977668, 2023). "The unusual m6A modification caused by differentially expressed METTL13 or METTL14 plays a critical role in the malignant progression of various cancers, such as bladder cancer, gastric cancer, and hepatocellular carcinoma (HCC)." (PMID 33159022, 2020). "In hepatocellular carcinoma (HCC), METTL14 downregulation is associated with tumor metastasis, but METTL3 enhances the invasive ability of HCC cells." (PMID 29061143, 2017). "Concurrently, METTL14 deficiency activates S100A4+ Macrophages through the myeloid differentiation primary response 88 (MyD88)/NF-κB signaling, ultimately driving hepatocellular carcinoma progression." (PMID 40986143, 2025). "Studies coupling YTHDF2 with METTL14 unveil that YTHDF2-mediated degradation of SLC7A11 mRNA necessitates METTL14-mediated RNA m6A modification in hepatocellular carcinoma." (PMID 40327848, 2025). "G6pc plasmid was cotransfected with METTL14 plasmid (empty plasmid as control) into Huh7 cells (human hepatoma line)." (PMID 40278833, 2025). "METTL14 suppresses the metastatic potential of hepatocellular carcinoma by regulating m6A‐dependent primary microRNA processing." (PMID 39006762, 2024). "In conclusion, our research results confirm the involvement of the METTL14-m6A mechanism in the regulation of CHOP-mediated cell cycle arrest in hepatocellular carcinoma." (PMID 38664644, 2024). "In HCC, METTL3 and METTL14 have opposing effects on the migration of hepatocellular carcinoma cells." (PMID 38166703, 2024).
hepatocellular carcinoma (continued). "METTL14, another m6A regulator, is shown to suppress the invasion and metastasis of hepatocellular carcinoma (HCC) through promoting the maturation of pri-miR-126." (PMID 36226036, 2022). "Our study demonstrated that METTL14 favours migration and invasion of CM cells, which is not contradictory to the activity of METTL3; for example, METTL3 and METTL14 can play opposing roles in the regulation of hepatocellular carcinoma." (PMID 36264762, 2022). "For example, in hepatocellular carcinoma, METTL14 can regulate the maturation of many essential miRNAs in cells through m6A modifications, thereby inhibiting the metastatic ability of hepatocellular carcinoma cells." (PMID 35733918, 2022). "Concerning METTL14, a previous study in hepatocellular carcinoma suggested a tumor suppressor function, contrarily to the oncogenic role in pancreatic and breast cancers." (PMID 35048498, 2022). "In regard to METTL14, currently available studies have demonstrated that it was significantly correlated with hepatocellular carcinoma, glioblastoma, acute myeloid leukemia, gastric cancer, and breast cancer." (PMID 35559023, 2022). "Different studies have reported that METTL14 suppressed progression and metastasis in several cancers, such as colorectal cancer and hepatocellular carcinoma." (PMID 36347025, 2022). "More detailed studies are needed, however, to characterize METTL3 and METTL14 in glioblastoma and hepatocellular carcinoma." (PMID 36360287, 2022). "For instance, METTL14 mediates the m6A-dependent processing to slacken the metastatic potential of hepatocellular carcinoma." (PMID 36288387, 2022). "Down-regulation of METTL14 is an adverse factor for recurrence-free survival and prognosis of patients with hepatocellular carcinoma." (PMID 35022030, 2022). "Recent professional research discovered the decreased tendency of m6A level in hepatocellular carcinoma after METTL14 expression inhibition." (PMID 35733918, 2022). "Low expression of METTL14 in hepatocellular carcinoma was related to poor prognosis and tumor metastasis through regulating pri-miR126." (PMID 34699322, 2021). "The results of Ma et al40 suggested that METTL14 is responsible for aberrant m6A methylation in hepatocellular carcinoma." (PMID 34164910, 2021). "METTL14 is the key methyltransferase responsible for m6A modifications, and has been demonstrated to inhibit the metastasis of hepatocellular carcinoma through m6A-dependent primary microRNA processing events." (PMID 33849617, 2021). "The results showed that the proliferation and migration of hepatocellular carcinoma cells were inhibited after METTL14 was knocked down in these cells." (PMID 34814861, 2021). "Using the CRISPR-Cas9 system to increase the expression of METTL14 promoted the proliferation and migration of hepatocellular carcinoma cells." (PMID 34814861, 2021). "The writer METTL3 and METTL14 were reported to promote tumorigenesis in hepatocellular carcinoma and acute myeloid leukemia (AML), but have the opposite effect in gastric cancer." (PMID 33796449, 2021). "According to another study, it has been proved that METTL14, a major RNA N6-adenosine methyltransferase, suppresses the metastatic potential of hepatocellular carcinoma by modulating m6A-dependent primary microRNA processing." (PMID 33430867, 2021). "For example, some researchers reported that in hepatocellular carcinoma, the expression of METTL14 is significantly downregulated, which reduces the overall m6A methylation level of RNA." (PMID 34814861, 2021). "METTL14 promotes the maturation of pri-miR-126 and suppresses the invasion and metastasis of hepatocellular carcinoma (HCC)." (PMID 32767982, 2020). "Consistent with our results, HNRNPA2B1 has been reported to act as an oncogene in breast cancer, pancreatic cancer, lung cancer, hepatocellular carcinoma, and cervical cancer, while METTL14 functions as a suppressor gene in glioma and breast cancer." (PMID 32582536, 2020).
hepatocellular carcinoma (continued). "In contrast, the potential role of METTL14 as an oncogene has also been observed in acute myelocytic leukemia and hepatocellular carcinoma." (PMID 32582536, 2020). "Serving as the key methyltransferase responsible for m6A modifications, METTL14 was demonstrated to suppress the metastatic potential of hepatocellular carcinoma via m6A-dependent primary microRNA processing events." (PMID 32843065, 2020). "In hepatocellular carcinoma tissue, a significant low expression of METTL14 has been found and correlated with metastasis inhibition." (PMID 30654440, 2019). "In hepatocellular carcinoma, METTL14 has been identified as a tumor suppressor that coprecipitates with DGCR8." (PMID 31757221, 2019). "Functionally, METTL14 was reported as a tumor suppressor for glioblastoma and hepatocellular carcinoma and ALKBH5 as oncogene for glioblastoma and BC." (PMID 30953473, 2019). "Two independent research groups have found that METTL14 exerts opposing biological functions in hepatic carcinoma." (PMID 31290116, 2019). "Rescue experiments showed that a miR-126 inhibitor promoted the metastatic ability of METTL14-overexpressing cells, which proved that miR-126 is a key regulator of the process by which METTL14 inhibits hepatocellular carcinoma progression." (PMID 31757221, 2019). "On the other hand, METTL14 plays an oncogenic role in acute myeloid leukemia, but suppresses the metastatic potential of hepatocellular carcinoma by modulating m6A dependent primary microRNA processing." (PMID 31607270, 2019). "Studies have shown that METTL14 often plays a tumor suppressive role in tumors such as hepatocellular carcinoma and colorectal cancer, while in pancreatic cancer and nasopharyngeal carcinoma, it mostly promotes malignant progression, showing a high degree of context dependence." (PMID 41858346, 2026). "METTL14 inhibited hepatocellular carcinoma metastasis by inducing miR-126 mature." (PMID 39867638, 2025). "Furthermore, overexpression of YTHDF1/2, YTHDC1, RBM15, and METTL3 is significantly correlated with the clinical stage of hepatocellular carcinoma, while downregulation of ZC3H13 and METTL14 is associated with poor prognosis." (PMID 38762484, 2024). "Furthermore, miR-628-5p exosomes derived from M1 macrophages inhibited human methyltransferase-like 14 (METTL14) expression in hepatocellular cancer, influencing the expression of circFUT8 and suppressing tumor progression." (PMID 39769441, 2024). "Studies discovered that m6A methylase METTL14 could regulate pri-miRNA processing by directly targeting DGCR8 in a way dependent on METTL14/m6A in hepatocellular carcinoma." (PMID 35733918, 2022). "Furthermore, m6A regulators, such as RBM15, METTL14 were also demonstrated to act as prognosis markers in multiple cancers, such as pancreatic cancer and hepatocellular carcinoma." (PMID 35847857, 2022). "In hepatocellular carcinoma, reduced METTL14 expression, but not METTL3 was associated with adverse patient prognosis and tumor metastasis by regulating the process of pri-miR126." (PMID 33430867, 2021). "Moreover, METTL14 inhibits the potential metastatic ability of hepatocellular carcinoma by regulating the microRNA process that depends on m6A methylation." (PMID 34476213, 2021). "As previously reported, METTL14 could serve as a suitable prognostic factor for clear renal cell, carcinoma cell, and hepatocellular carcinoma." (PMID 34476213, 2021). "The inhibitory role of METTL14 on hepatocellular carcinoma may be partly attributed to its facilitation of the primary miR-126 maturation in a m6A-dependent manner." (PMID 34863142, 2021). "For example, in hepatocellular carcinoma, RFS is adversely affected by downregulated levels of METTL14 expression, while a reduction in m6A mRNA methylation caused by the METTL14 loss-of-function R298P mutation increases the proliferation and tumorigenicity of endometrial cancer cells." (PMID 33134390, 2020).
hepatocellular carcinoma (continued). "Therefore, METTL14 has an important role in inhibiting metastasis of hepatocellular carcinoma by regulating pri-miRNA." (PMID 33292652, 2020). "Similarly, METTL14 seems to play an oncogenic function in acute myeloid leukemia, but in hepatocellular carcinoma, it behaves as metastasis suppressor by modulating m6A dependent microRNA processing." (PMID 32218194, 2020). "By contrast, METTL14 was down-regulated in colorectal cancer and hepatocellular carcinoma and could inhibit cancer cells’ growth and metastasis by regulating m6A-dependent primary microRNA processing." (PMID 33363011, 2020). "In this study, we found that METTL14 may inhibit the progression of hepatocellular carcinoma (HCC) by up‐regulating the expression levels of cysteine sulfinic acid decarboxylase, glutamic‐oxaloacetic transaminase 2, and suppressor of cytokine signaling." (PMID 31943856, 2020). "METTL14 expression could also increase the tumorigenesis of glioblastoma stem cells but suppress the metastatic potential of hepatocellular carcinoma." (PMID 30953473, 2019). "However, a study had demonstrated that m6A modification was decreased in hepatocellular carcinoma, especially in metastatic hepatocellular carcinoma, and METTL14 was the main factor involved in aberrant m6A modification." (PMID 31870368, 2019). "Previous study revealed that methyltransferase-like 14 (METTL14) could suppress the metastatic potential of hepatocellular carcinoma by modulating m6A dependent primary microRNA processing." (PMID 31159832, 2019). "Additional writers and readers, such as METTL14 in hepatocellular carcinoma (HCC), stabilize oncogenic transcripts like SIRT6." (PMID 40761481, 2025). "METTL14 is central to various common cancers, including hepatocellular carcinoma (HCC), breast cancer (BC), prostate cancer, glioma, and leukemia, nonsmall cell lung cancer (NSCLC)." (PMID 41316520, 2025). "Studies have shown that METTL14 promotes pri-miR-126 maturation through the recruitment of DGCR8-dependent m6A in hepatocellular carcinoma (HCC)." (PMID 40734692, 2025). "Exosomes from M1 macrophages transfer miR-628-5p to hepatocellular carcinoma (HCC) cells, inhibiting the expression of human methyltransferase-like 14 (METTL14)." (PMID 40034694, 2025). "In hepatocellular carcinoma(HCC), intestinal bacterial lipopolysaccharide regulates the expression of PD-L1 on the surface of cancer cells by upregulating METTL14 and METTL14-mediated m6A modification of MIR155HG, modulating the miR-223/STAT1 axis." (PMID 39372415, 2024). "Studies showed that METTL14 acts as a tumour suppressor gene in hepatocellular carcinoma (HCC) and colorectal cancer (CRC)." (PMID 36567510, 2023). "As a suppressor in hepatocellular carcinoma (HCC), METTL14 interacts with DGCR8 to promote the processing of pri-miR-126 via an m6A-dependent pattern, triggering the enhanced level of miR-126 which represses the tumor metastasis." (PMID 33754077, 2021). "METTL14 has also been shown to be involved in the regulation of miRNAs processing in the context of hepatocellular carcinoma (HCC), where it prevents cancer progression." (PMID 33564819, 2021). "In hepatocellular carcinoma (HCC), METTL14 has been proven to promote pri-miR-126 processing, while METTL14 depletion in HCC cells reduces m6A levels and miR-126 expression, leading to cancer cell migration and invasion." (PMID 32443966, 2020). "However, METTL3 and METTL14 play opposite regulatory roles in hepatocellular carcinoma (HCC)." (PMID 33159022, 2020). "In one study it has been shown that, METTL14 knockdown in hepatocellular carcinoma (HCC) enhances the metastatic tumor progression by decreasing m6A mRNA level both in vivo and in vitro." (PMID 32194861, 2020). "METTL14 is an anti-metastasis factor in primary Hepatocellular carcinoma (HCC), and down-regulation of METTL14 suggests poor prognosis in HCC patients and leads to HCC progression and metastasis." (PMID 33237039, 2020).